MFGE8 (milk fat globule EGF and factor V/VIII domain containing)
Diseases named in the same sentence as MFGE8 in open-access papers (continued):
Sharing a sentence is not in itself a finding about the gene and the disease.
tumor (43 papers, 2012 to 2025). "ROC analyses were performed to evaluate the diagnostic discriminatory potential of DJ-1, GDF15, and MFGE8 gene expressions based on tumour grade." (PMID 41009755, 2025). "ROC analyses were performed to evaluate the diagnostic performance of the DJ-1, GDF15, and MFGE8 genes in discriminating tumour diameter." (PMID 41009755, 2025). "Next, we downloaded and analyzed BC patient and BC cell line data from TCGA directly or the UCSC Xena database to evaluate the association of MFGE8 mRNA and lactadherin protein levels with histologic BC subtypes, tumor stage, and PAM50 subtypes." (PMID 38173019, 2024). "Considering the tumor specificity and frameshift mutation, we selected MFGE8-HAPLN3 as a novel biomarker and further validated it in TNBC samples using PCR and Sanger sequencing." (PMID 34211850, 2021). "Given these properties, MFGE8 has been studied as an inducer of tumor metastasis, and tumor cells and myeloid cells such as tumor-associated macrophages (TAMs) are thought to be the main source of MFGE8." (PMID 34440100, 2021). "From this list, we additionally selected the C1C2 domain of MFGE8 and Lamp2b since they have been previously used as sorting domains to load EVs with tumour-associated antigens and tissue-specific targeting peptides respectively." (PMID 31579435, 2019). "Regarding tumour size, only MFGE8 expression showed a significant correlation, while DJ-1 and GDF15 did not exhibit statistically meaningful associations." (PMID 41009755, 2025). "Milk fat globule‐EGF factor 8 (MFGE8) is a key protein in OCDMs and MANPs, MFGE8 knockdown in OCDMs and MANPs inhibits the tumor‐promoting effects of macrophages." (PMID 40056029, 2025). "Supporting this notion, literature reports have described MFGE8 as having diverse functions, including angiogenesis and immune modulation within the tumour microenvironment." (PMID 41009755, 2025). "Using RT-qPCR analysis, the expression levels of DJ-1, GDF15, and MFGE8 genes were evaluated according to sex, tumour grade, tumour diameter, and Ki-67 Pi." (PMID 41009755, 2025). "This difference is also attributed to the fact that vSSCs produce high levels of the protein milk fat globule EGF (Mfge8), which effectively stimulates the migration ability of tumor cells." (PMID 38442300, 2024). "Open-source microarray data showed that tumor-infiltrated MDSCs also express higher levels of MFGE8 mRNA than splenic MDSCs (Figure A1)." (PMID 34440100, 2021). "Previous studies have shown that MFGE8 promotes tumor progression or metastasis in various cancer models, yet the reported source of MFGE8 was mainly TAMs or stromal cells." (PMID 34440100, 2021). "Mfge8 was selected as a target gene of interest because Mfge8 had the largest ‘Distance’ value when recalculated with the qPCR results (Table A1), and because Mfge8 has an anti-inflammatory function as well as a role in promoting tumor metastasis." (PMID 34440100, 2021). "In this study, we demonstrate that MDSCs are a source of milk fat globule-epidermal growth factor (EGF) factor 8 (MFGE8), which is known to be involved in tumor metastasis." (PMID 34440100, 2021). "TAMs produced large amounts of both MFGE-8 and IL-6, which coordinately induced tumor potential and CSC chemoresistance through STAT3 and Hedgehog signaling, the latter of which regulates normal stem cell self-renewal." (PMID 26980947, 2016). "The IL-6/STAT3 pathway was also shown to increase tumor-initiating activities in murine colon and lung cancer cell lines by milk fat globulin epidermal growth factor-8 (MFGE-8)." (PMID 26980947, 2016). "A component of polycomb repressor complex 2, enhancer of zeste homolog 2 (EZH2), plays an important role in tumor malignancy and metastasis, while milk fat globule-epidermal growth factor-factor 8 (MFGE8) plays a key role in tumor progression and prognosis." (PMID 25081869, 2014).
tumor (continued). "On some tumor cells themselves, MFGE8 was shown to induce epithelial to mesenchymal transition, and/or to increase resistance to drug-induced apoptosis." (PMID 23977342, 2013). "We have previously shown that human MFGE8 promotes AKT signaling in human endothelial cells, both directly, and by potentiating VEGF-induced signaling : MFGE8 thus represents another pro-angiogenic molecule in the tumor microenvironment." (PMID 23977342, 2013). "The combined analysis of 3 physiological effects of MFGE8/lactadherin on tumor cells, i.e. adhesion, migration and survival, allowed us to rank 5 different MFGE8-specific antibodies, and to compare them to the reference antibody hMc3." (PMID 23977342, 2013). "MFGE8, initially identified on the surface of milk fat globules, is a transmembrane glycoprotein involved in various processes, including inflammation, immunity, apoptosis, proliferation, and tumor progression." (PMID 40895313, 2025). "Comparison of gene expression levels between these groups may provide insights into the potential roles of DJ-1, GDF15, and MFGE8 in tumour progression, malignant transformation, and poor prognosis." (PMID 41009755, 2025). "Deletion of Mfge8 can significantly reduce the tendency of tumor cells to metastasize to the spine." (PMID 38442300, 2024). "MFGE8 expression was decreased in tumor tissues in BLCA and KIRP, predicting better OS." (PMID 36059952, 2022). "Our results showed that high expression of MFGE8 in tumor tissues was also associated with worse OS in PAAD and STAD, which indicated that MFGE8 may serve as a potential target in these cancers." (PMID 36059952, 2022). "Therefore, our findings suggest a new mechanism through which MDSCs promote tumor progression, as a source of MFGE8." (PMID 34440100, 2021). "Furthermore, MFGE8 knockdown significantly inhibited both migration and proliferation of tumor cells, attenuating their tumorigenic properties." (PMID 34211850, 2021). "Protein–protein interaction analysis by affinity purification mass spectrometry (AP-MS) and proximity biotinylation (BioID) experiments identified a role for TBC1D9 in maintaining cellular integrity, whereas MFGE8 would be involved in various tumor survival processes." (PMID 32591639, 2020). "However, the increased expression of MFGE8 protein in the tumor environment not only increased the efferocytosis, but also promoted the initiation, development and metastasis of tumor." (PMID 33597922, 2020). "Interestingly, the bile ducts within the metastases and the normal parenchyma were also strongly positive for MFGE8 with some mUM showing a proliferation of bile ducts in the tumour within areas of desmoplasia." (PMID 33008022, 2020). "MFGE8 is reported to be involved in tumor progression and prognosis." (PMID 29657263, 2016). "Recent studies demonstrated that MFGE8 correlated with tumor malignancy and microenvironment." (PMID 25081869, 2014). "In addition, mouse macrophages within transplanted tumors or after activation by inflammatory signals secrete high levels of Mfge8, which have been shown to help tumor cells, especially cancer stem cells, resist apoptosis." (PMID 23977342, 2013). "Thus rather than inducing migration by inducing acquisition of a mesenchymal state, or by binding to phosphatidylserine at the cell surface, as described for intestinal epithelial cells, MFGE8 here is instead a chemoattractant for tumor cells." (PMID 23977342, 2013). "Using these assays, we could identify new MFGE8-specific monoclonal antibodies, which efficiently blocked these three tumor-promoting effects of MFGE8." (PMID 23977342, 2013). "Additionally, investigating the proteomic effects of DJ-1, GDF15, and MFGE8, as well as their interactions with the tumour microenvironment, could provide a more comprehensive understanding of the clinical relevance of their expression profiles." (PMID 41009755, 2025).
tumor (continued). "However, the relatively limited correlation between MFGE8 expression and tumour grade suggests that the former’s role may be complex and multifactorial." (PMID 41009755, 2025). "Meanwhile, apoptotic tumor cells display “eat-me” signals such as phosphatidylserine and calreticulin, which are recognized by receptors in macrophages responsible for efferocytosis, such as milk fat globule-epidermal growth factor-factor 8 (MFGE8), MerTK, Axl, and Tyro3." (PMID 38802814, 2024). "Furthermore, previous studies found that MFGE8 could promote tumor progression and might be a novel biomarker for the diagnosis of patients with HCC." (PMID 36314455, 2022). "Furthermore, MFGE8 produced by MDSCs may also be involved in the inhibition of T cell proliferation in the tumor microenvironment, as a previous report showed inhibition of T cell proliferation by MFGE8." (PMID 34440100, 2021). "In addition, we hypothesize that the potential synergistic effects of COX-2 inhibition and some genes KO (KLK5/7, MFGE8) on suppressing TNBC primary tumor growth might be due to convergent inhibition of different aspects of tumorigenesis." (PMID 33588911, 2021). "Thus, blocking MFGE8 may be also a promising approach in combination with some chemotherapies to allow destruction of the most resistant tumor cells." (PMID 23977342, 2013). "Activated macrophages exerted anti-tumor effects by producing inflammatory cytokines like IL-1β, while the interaction between ITGB3 and MFGE8 inhibited macrophage IL-1β production by inducing necrotic cells and an ATP-dependent manner." (PMID 38183097, 2024). "On the other hand, patients with higher tumor stages (III and IV) and high MFGE8 transcription had worse survival than patients with low MFGE8 transcription (brown and orange curves)." (PMID 38173019, 2024). "Taken together, these findings suggest that MFGE8 is an important effector molecule through which MDSCs promote tumor metastasis, and the TME positively regulates MFGE8 production by MDSCs through TGF-β." (PMID 34440100, 2021). "Interestingly, PyMT tumor cells that were proximal to the C6:LP-NP cluster exhibited elevated Aldh1a3 expression, whereas there was an enrichment of cells with high Mfge8 expression towards the C7:LP-PI cluster, suggesting that the post-involution state is associated with increased Mfge8 expression." (PMID 32840210, 2020). "When evaluated in terms of tumour size, only GDF15 expression demonstrated a statistically significant association, whereas no such relationship was observed for DJ-1 and MFGE8." (PMID 41009755, 2025). "Furthermore, activated CAFs release SDF-1/CXCL12, OPN, periostin, galectin, THBS2, MFGE8, and diverse cytokines such as IL-6 and IL-32, which promote the EMT, tumor invasion, and tumor metastasis." (PMID 40352270, 2025). "However, interestingly, BC patients with higher tumor stages (III and IV) and high MFGE8 levels had worse survival than MFGE8 low patients." (PMID 38173019, 2024). "Interestingly, TGF-β, an abundant cytokine in the tumor microenvironment (TME), increased MFGE8 production by MDSCs." (PMID 34440100, 2021). "Although MFGE8 did not increase the immunosuppressive function of MDSCs, it has been previously reported that MFGE8 induces tumor metastasis in various models." (PMID 34440100, 2021). "Furthermore, we found MFGE8, KLK5, and KLK7 knockout (KO) to restore celecoxib sensitivity in TNBC cells leading to marked reductions in primary tumor growth." (PMID 33588911, 2021). "In a cancer hypoxic condition, MFGE8 might interact with OS9 and therefore releasing HIF1α, resulting in tumor growth and metastasis." (PMID 32591639, 2020). "Thus MFGE8 promotes survival only in the presence of very low FCS levels, mimicking the starvation conditions inside a poorly vascularized tumor." (PMID 23977342, 2013).
tumor (continued). "Surprisingly, secretion in the 100,000 g pellet of CD9 and Mfge8, 2 other markers classically used to characterize mouse dendritic or tumor cell exosomes, was not reduced in shRab27a-expressing cells." (PMID 24009879, 2012). "In addition, our results show that MFGE8 and TSPAN4 are highly expressed in OS tissues compared to corresponding non‐tumor tissues, and are highly expressed in lung metastatic tissues compared to corresponding tumor tissues." (PMID 40056029, 2025). "Gene expression levels of DJ-1, GDF15, and MFGE8 were increased in tumours larger than 6 cm in diameter, with the most prominent and statistically significant increase observed in the GDF15 gene (p = 0.556, p = 0.042, and p = 0.053 for DJ-1, GDF15, and MFGE8, respectively)." (PMID 41009755, 2025). "Finally, MFGE8-HAPLN3 (16.7% in TNBC tumor tissues vs. 3.5% in adjacent normal breast tissues) was screened out." (PMID 34211850, 2021). "Thus determining the role of MFGE8 and of the MFGE8-blocking agents in the physiology of non-tumoral cells present within the human tumor microenvironment will be another important issue to address, to use them in the best conditions in clinical settings." (PMID 23977342, 2013). "The observed spatial expression patterns suggest that marginal tumor nest cells might engage in immune escape by activating immune regulatory pathways through close interactions with immune cells and the TME (Such as the gene MFGE8, which is a potent pro-angiogenic factor." (PMID 40741331, 2025). "According to our analysis, MFGE8 does not affect body development and function under normal physiological conditions but can play specific role through its multiple domains at different pathway levels when different pathological pressures occur, such as inflammation, tumour and ischaemia." (PMID 32945126, 2020).
cancer (24 papers, 2013 to 2025). A tumor composed of atypical neoplastic, often pleomorphic cells that invade other tissues. "Consistently, in comparison with normal counterparts, the splicing of MFGE8 is shifted towards a reduced proportion of MFGE8-L across multiple cancer types, including LUAD, HNSC, COAD, etc." (PMID 38995840, 2024). "The high expressions of Gas6 and MFGE8 were associated with the high ESTIMATE score and stromal score in certain types of cancers." (PMID 36059952, 2022). "To elucidate the significance of PC4 with respect to SMYD3 transactivation, we next investigated PC4 localization at the FNBP1 and MFGE8 genes by ChIP assays employing cross-linked chromatin isolated from control and SMYD3-depeleted cancer cells." (PMID 26350217, 2015). "The expression levels of miRs complementary to EZH2 and MFGE8 mRNA and cancer malignancies were evaluated." (PMID 25081869, 2014). "Together, these findings suggest that MDSC-derived MFGE8 could be a valuable target for cancer therapies." (PMID 34440100, 2021). "Thus, generating new tools to inhibit the pleiotropic functions of MFGE8, as well as identifying the right human cancer targets of such tools, must be performed simultaneously if we hope to achieve efficient new therapies." (PMID 23977342, 2013). "Except for BAI1, CD31, and MerTK, the enhanced expression of Axl, Tyro3, Gas6, MFGE8, Stab2, Tim-4, CX3CL1, IDO1, Rac1, and PD-L1 was associated with decreased sensitivity to many drugs, which may partially explain the resistance to chemotherapy in cancers." (PMID 36059952, 2022). "Therefore, we hypothesized that MFGE8, as an effector molecule of MDSCs, may promote cancer metastasis in TGF-β-rich environments such as the TME." (PMID 34440100, 2021). "Inhibiting the functions of MFGE8 could thus represent a new type of therapy for human cancers." (PMID 23977342, 2013). "The main role in the TAM-cancer cell crosstalk is played by production of factors such as MMPs, IL-1β, IL-10, VEGF, PDGF, TGF-β1, MFGE-8, CCL-17, -22, arginase-I and galectin-3." (PMID 30925774, 2019). "In particular, human vSSCs secreting MFGE8 were more likely to interact with cancer cells than were those vSSCs that were not secreting the protein." (PMID 38256412, 2024). "Finally, we depleted Thy1 and MFGE8 from CAFs and we tested whether tracks lacking these two proteins could still orient cancer cell migration." (PMID 37585527, 2023).
infection (6 papers, 2019 to 2025). The state of being infected such as from the introduction of a foreign agent such as serum, vaccine, antigenic substance or organism. "STm infection induced a noticeable expansion of MadCAM-1+ cells from 7 days up to 28 days after the infection, and these cells were detected not only in the MZ but also in the follicles, and some were positive for Mfge-8." (PMID 36950118, 2023). "MFGE8 mRNA expression was increased in Mo-MDSCs and Gr-MDSCs upon infection with the MFGE8-expressing retrovirus compared with cells infected with the vector control retrovirus." (PMID 34440100, 2021). "Overexpression of MFGE8 enhances the pseudotyped, tecVLP, and authentic CCHFV infection, while knockout decreases the infection." (PMID 40852990, 2025).
neurodegenerative disease (3 papers, 2018 to 2024). A disorder of the central nervous system characterized by gradual and progressive loss of neural tissue and neurologic function. "Increased expression levels of the MFGE8 gene in MPS cells are consistent with other neurodegenerative disease findings involving this gene." (PMID 38534785, 2024). "The need to study MFGE8 signaling pathways as a possible drug candidate for the bedside management of neurodegenerative diseases has been highlighted." (PMID 38534785, 2024).
cardiovascular disorder (1 paper, 2022). A disease involving the cardiovascular system. "A missense variant is MFGE8 is also found to be associated with T2D and cardiovascular disorders." (PMID 35987697, 2022).
intestinal disease (1 paper, 2023). "Our study suggests that alterations in MFGE8 function may contribute to HFD-associated intestinal disease." (PMID 36538527, 2023).
MFGE8 also shares sentences with these, for which no sentence is quoted: diabetes (7 papers); Cerebral ischemia (4); ischemic stroke (4); cerebral amyloid angiopathy (3); depression (3); inflammation (3); Parkinson disease (3); bladder tumors (2); Brain atrophy (2); brain disorder (2); cardiac ischemia (2); endometriosis (2); hepatocellular carcinoma (2); Infertility (2); inflammatory bowel disease (2); pulmonary fibrosis (2); renal fibrosis (2); systemic sclerosis (2); acute lung injury (1); adenocarcinoma (1); adenoma (1); age (1); airway hyperresponsiveness (1); alcohol (1); allergic asthma (1); anaplastic breast carcinoma (1); angiosarcoma (1); Anxiety (1); anxiety disorder (1); artery stenosis (1).
A further 39 diseases each share a sentence with MFGE8 in 1 paper.